USP24 (ubiquitin specific peptidase 24)
Diseases named in the same sentence as USP24 in open-access papers (continued):
Sharing a sentence is not in itself a finding about the gene and the disease.
lung carcinoma (continued). "However, whether USP24-i-101 is also effective on other genomic types of lung cancer, such as KrasG12D or other cancer types in vivo, needs to be clarified in the future." (PMID 38491202, 2024). "In addition, USP24 promoted lung cancer malignancy by stabilizing proteins containing bromodomains." (PMID 35223996, 2022). "The DisGeNET knowledge platform’s analyses found USP24 dysregulation to be associated with LDL-C levels (gene-disease score, GDA = 1), Parkinson disease (GDA 0.08), and various cancer types (GDA = 0.04–0.01) including lung cancer, multiple myeloma, T-cell lymphoma, and neuroblastoma." (PMID 36580462, 2022). "All these results indicated that regulation of the levels of BRD-containing proteins by USP24 is important for the function of USP24 in cancer progression, including its inhibition of cellular proliferation and increase in cancer migratory ability in lung cancer and bone cancer cells." (PMID 33257797, 2020). "Together, elevated USP24 levels indicate PD-1 abundance and T cell dysfunction, which contributed to worse clinical outcomes and poor ICB responses in patients with lung cancer." (PMID 40238877, 2025). "Together, high infiltration of USP24+PD-1+CD8+ T signature indicates T cell dysfunction and worse clinical outcomes in lung cancer." (PMID 40238877, 2025). "Our recent studies also indicated that USP24 can regulate CD44, which is also involved in the ECM of lung cancer." (PMID 38491202, 2024). "In this study, we found that targeting USP24 by USP24-i-101 can dramatically induce autophagy through upregulation of ULK1, LC3 and ULK phosphorylation at Ser555 in lung cancer to negatively regulate drug resistance." (PMID 38491202, 2024). "Herein, we found that knockdown of USP24 by shUSP24 or targeting USP24 by the USP24 inhibitor USP24-i in A549-T24 and PC9-GR drug-resistant lung cancer cell lines increased the LC3 levels but decreased the E2F4 levels." (PMID 38491202, 2024). "We not only studied the role of USP24 in cancer cells, also studied it by using lung cancer animal model, EGFRL858R, treated with gefitinib and USP24-i-101 for a long time." (PMID 38491202, 2024). "In summary, USP24-i targeting USP24 activates autophagy to promote the degradation of ABCG2 and PD-L1, leading to the inhibition of drug resistance acquired from lung cancer therapy." (PMID 38491202, 2024). "Recently, we developed a novel USP24 small‐molecule inhibitor, NCI677397, to overcome Taxol‐induced drug‐resistant lung cancer." (PMID 38140768, 2024). "Our previous studies indicated that USP24 promotes drug resistance during cancer therapy and leads to the development of a novel USP24‐specific small‐molecule inhibitor, NCI677397, to suppress drug resistance, especially in lung cancer." (PMID 38140768, 2024). "The relationship among USP24, ABCG2, and cancer stemness markers was then studied in clinical lung cancer cohorts." (PMID 33846536, 2021). "The data indicated a highly positive correlation between the levels of USP24 and ABCG2 in patients with lung cancer." (PMID 33846536, 2021). "We continued to use this construct to study the role of the interaction between USP24 and BRD-containing proteins in lung cancer progression." (PMID 33257797, 2020). "Data indicated that higher USP24 level led poor prognosis significantly, but only slightly relevance in BRD7 level in lung cancer progression." (PMID 33257797, 2020). "As most of the previous studies about USP24 were performed in U2OS cells, herein we not only use lung cancer cell lines but also use U2OS to study the role of USP24 in tumorigenesis." (PMID 27991932, 2017). "In addition to the gene expression involved in lung cancer progression, other genes related to other pathways involved in hematopoietic disease, dermatomyositis, leukocyte migration/cell-cell adhesion/chemotaxis and fat cell differentiation might also be related to USP24-mediated drug resistance." (PMID 38491202, 2024).
lung carcinoma (continued). "The compound WP1130, which can inhibit lymphoma progression, did not inhibit USP24 activity with these substrates in lung cancer." (PMID 33846536, 2021). "Finally, we also studied the effect of the interaction between USP24 and BRD-containing proteins on the migratory ability of lung cancer and bone cancer cells." (PMID 33257797, 2020). "Analysis of p300 and NF-κB levels in cancer cells showed that p300 but not NF-κB was decreased after USP24 knockdown, implying that there are distinct mechanism(s) regulating IL-6 expression in M2 macrophages and lung cancer cells." (PMID 30266897, 2018). "USP24 stabilizes p300 and β-TrCP to increase the levels of histone-3 acetylation and NF-κB, and decreases the levels of DNMT1 and IκB, thereby increasing IL-6 transcription in M2 macrophages and lung cancer cells, results in cancer malignancy finally." (PMID 30266897, 2018). "Here, the authors demonstrate that USP24 stabilizes p300 and β-TrCP to increase the levels of NF-κB and histone-3 acetylation, and decrease DNMT1 and IκB levels which promotes IL-6 expression in M2 macrophages and lung cancer cells." (PMID 30266897, 2018). "However, an increase in p300 by USP24 enhances the NF-κB level through an increased recruitment of acetyl histone H3 to the promoter of NF-κB to regulate IL-6 expression in M2 macrophages but not in lung cancer cells." (PMID 30266897, 2018). "A negative correlation between USP24 and DNMT1 was observed in human lung cancer specimens." (PMID 30266897, 2018).
Parkinson disease (9 papers, 2018 to 2026). A progressive degenerative disorder of the central nervous system characterized by loss of dopamine producing neurons in the substantia nigra and the presence of Lewy bodies in the substantia nigra and locus coeruleus. "USP24 has previously been associated with Parkinson's disease and has recently emerged as a candidate risk gene for ASD." (PMID 42123666, 2026). "Several studies have shown that single nucleotide polymorphisms (SNPs) of USP24 are correlated with Parkinson’s disease." (PMID 40448065, 2025). "The function of USP24 is poorly understood, and most studies examining USP24 have focused on the single nucleotide polymorphisms (SNPs) of USP24 implicated in Parkinson’s disease (PD)." (PMID 40448065, 2025). "USP24 is implicated in Parkinson’s disease and increased autophagy, but expression data presented here indicate a role for USP24 in heart, nerve, and muscle tissue, but not adipose or brain tissues." (PMID 35501368, 2022). "One of these mutations was found in PHLPP1, which has been associated with colorectal cancer, and the other was found in USP24, which has been associated with Parkinson’s disease." (PMID 36510265, 2022). "Several reports show that USP40 is correlated with late-onset Parkinson’s disease and USP24." (PMID 31046799, 2019). "Because autophagic inhibition was found in most neurodegenerative diseases, such as Parkinson’s disease (PD) and Alzheimer’s disease (AD), the specific USP24 inhibitor, USP24-i-101, might be also work to prevent PD and AD, which needs to be clarified in the future." (PMID 38491202, 2024).
myeloma (5 papers, 2020 to 2024). "Direct USP24 knockdown resulted in apoptosis of myeloma cells associated with a reduction in MCL1 levels." (PMID 32354135, 2020). "USP24 has anti-apoptotic tumoral activity in myeloma cells and is overexpressed in drug-resistant cells." (PMID 39664521, 2024). "USP24 has been shown to play a role in anti-apoptotic tumoral activity in myeloma cells and displayed increased expression in cells displaying increased drug resistance." (PMID 32457837, 2020). "Peterson and colleagues suggested that dual inhibition of USP9X and USP24 by WP1130 provides greater anti-myeloma activity." (PMID 32354135, 2020). "USP24, which is closely related to USP9X, also plays a critical role in the survival of myeloma B cells by regulating MCL1 protein levels." (PMID 32354135, 2020). "However, upregulation of USP24 in response to USP9X knockdown, promoting myeloma cell survival, demonstrated the need for dual USP9X/USP24 inhibitors, prompting the development of EOAI3402143 (aka G9) by improving the properties of WP1130." (PMID 34203106, 2021).
neuroblastoma (5 papers, 2022 to 2025). Neuroblastoma (NB) is the most common solid, extracranial childhood tumor. "In the context of neuroblastoma, a deficiency in USP24 is noted, and the overexpression of USP24 has been demonstrated to suppress the proliferation of neuroblastoma cells." (PMID 40607251, 2025). "USP24 is encoded on chromosome 1p32.3 – and area of the genome that is frequently lost in neuroblastoma tumors." (PMID 36338721, 2022). "The low expression of USP24 has been associated with poor survival in neuroblastoma." (PMID 37170124, 2023). "In contrast, USP24 has also been reported to act as a tumor suppressor in neuroblastoma." (PMID 40715045, 2025). "Moreover, USP24 was found to be frequently deleted in neuroblastoma, providing a clue that USP24 may be a critical factor for neuroblastoma pathogenesis." (PMID 37170124, 2023). "Through a computational screen, we found that low levels of the de- ubiquitinating enzyme USP24 have a highly significant negative impact on survival in neuroblastoma." (PMID 36338721, 2022).
bladder cancer (4 papers, 2021 to 2024). "Mass spectrometry of GSDMB indicated that GSDMB may interact with USP24, which was verified in bladder cancer cells through immunoprecipitation." (PMID 34326684, 2021). "In conclusion, USP24 stabilizes GSDMB to promote STAT3 phosphorylation in bladder cancer cells." (PMID 34326684, 2021). "Therefore, the USP24/GSDMB/STAT3 axis may be a new targetable signaling pathway for bladder cancer treatment." (PMID 34326684, 2021). "In bladder cancer, the USP24/GSDMB/STAT3 axis is reported to promote tumor proliferation and growth, where USP24 interacts and stabilizes GSDMB, which in turn binds to STAT3, increases its phosphorylation and activates STAT3 signaling." (PMID 35479097, 2022). "Here, our results indicated that USP24 bound to GSDMB to stabilize GSDMB, and subsequently activated the STAT3 pathway in bladder cancer cells." (PMID 34326684, 2021). "We proved that knocking down or inhibiting USP24 increased the polyubiquitination of GSDMB, but overexpressing USP24 decreased the polyubiquitination of GSDMB in bladder cancer cells." (PMID 34326684, 2021). "Contrary, the interaction between ubiquitin-specific peptidase 24 (USP24) and GSDMB prevents the degradation of gasdermin B in bladder cancer, and this may be a potential therapeutic target in the future." (PMID 39766111, 2024). "Furthermore, we also demonstrated that USP24 interacted with GSDMB and prevented GSDMB from degradation in bladder cancer cells." (PMID 34326684, 2021). "USP24 interacts with GSDMB and acts as a deubiquitinating enzyme (Dub) to remove polyubiquitin chains from GSDMB,304 increasing the stability of GSDMB in bladder cancer and further promoting downstream phosphorylation of STAT3, which promotes bladder cancer cell proliferation." (PMID 38584157, 2024). "Given that USP24 promoted the expression of the GSDMB protein levels rather than that of the mRNA levels in bladder cancer cells, we hypothesized that USP24 may regulate the stability of GSDMB through the ubiquitinated proteasome pathway." (PMID 34326684, 2021). "We further showed that USP24 inhibitors could block this process via inducing GSDMB degradation in cancer cells, which provided a therapeutic strategy for inhibiting the GSDMB/STAT3 axis in bladder cancer." (PMID 34326684, 2021). "Furthermore, we showed that USP24 could stabilize GSDMB, and the USP24/GSDMB/STAT3 signaling axis provided some potential therapeutic targets for bladder cancer." (PMID 34326684, 2021). "Although we genetically silenced USP24 to prove the stabilization of GSDMB by USP24, we could not rule out that USP9x or USP5 acted as deubiquitinases of GSDMB in bladder cancer." (PMID 34326684, 2021).
HCMV infection (3 papers, 2021 to 2023). "USP24 regulated and stabilized the protein levels of NCOA4 thereby promoting ferritinophagy during HCMV infection, while the binding of USP24 to pUL38 was able to reduce ferritinophagy to promote iron-dependent ER stress-induced cell death." (PMID 38075884, 2023).
Alzheimer disease (2 papers, 2022 to 2024). A progressive, neurodegenerative disease characterized by loss of function and death of nerve cells in several areas of the brain leading to loss of cognitive function such as memory and language. "In addition to PCSK9, expression data highlights the roles of DHCR24 and USP24 in SMI and CMD: DCHR24 has been shown to have a neuroprotective role during inflammation with loss-of DCHR24 expression being observed in Alzheimer’s disease." (PMID 35501368, 2022).
B-cell lymphoma (2 papers, 2020 to 2024). "When compared with control spleen and other B-cell lymphoma subtypes, significantly higher expression was noticed in SMZL samples when stained for EME2 and USP24." (PMID 32457837, 2020).
breast carcinoma (2 papers, 2024 to 2025). "We examined USP24 expression in breast cancer (including TNBC) versus normal tissues using publicly available gene and protein databases." (PMID 40715045, 2025). "In addition, breast cancer patients with elevated USP24 expression appear to have improved long-term survival outcomes." (PMID 40715045, 2025). "The results showed that RSL3 did not alter USP24 expression in these breast cancer cells, suggesting that ferroptosis-induced USP24 downregulation is cell-type selective." (PMID 40715045, 2025).
diabetes (2 papers, 2012 to 2025). "Several lipocalin (LCN)-like genes, such as Mup1, Mup3, Mup12, Mup15, Mup16, Mup7, Mup11, Mup17 and Mup14, had upregulated expression induced by USP24-i-101 treatment, which is consistent with the inhibition of obesity and diabetes." (PMID 40448065, 2025). "In summary, USP24 expression not only facilitates fatty liver but also facilitates the accumulation of visceral adipose tissue (VAT) around organs and subcutaneous adipose tissue (SAT), which induces several related diseases, such as liver cirrhosis, cardiovascular disease, and diabetes." (PMID 40448065, 2025). "Many lipogenesis-related diseases, such as fatty liver, hyperinsulinism, diabetes, and dyslipidemia, were significantly inhibited in USP24C1695A -overexpressed or USP24-i-101-treated HFD-fed mice, implying that targeting USP24 might prevent these diseases (p < 0.00005)." (PMID 40448065, 2025).
hepatocellular carcinoma (2 papers, 2025). A malignant tumor that arises from hepatocytes. "Intriguingly, USP24 uniquely promotes ferroptosis in hepatocellular carcinoma by removing ubiquitination from Beclin1, a core autophagy regulator." (PMID 40715045, 2025). "In hepatocellular carcinoma (HCC), the ubiquitin-specific peptidase 24 (USP24) deubiquitinates and stabilizes TRAF2, which, in turn, promotes cell proliferation and metastasis." (PMID 40229245, 2025). "By cleaving ubiquitin from substrates, USP24 influences the stability, localization, and interactions of various proteins, including PLK1, TRAF2, Beclin1, and GSDMB, in cancers such as gastric carcinoma, hepatocellular carcinoma, and bladder cancer." (PMID 40715045, 2025).
virus infection (2 papers, 2024). "In virus infection, human cytomegalovirus protein pUL38 binds to host protein ubiquitin-specific protease 24 (USP24), inhibiting NCOA4-mediated ferritinophagy against host fibroblasts cell death." (PMID 38961066, 2024).
acute lymphoblastic leukemia (1 paper, 2021). Leukemia with an acute onset, characterized by the presence of lymphoblasts in the bone marrow and the peripheral blood. "USP24 was also found to be one of targets of WP1130 T-cell acute lymphoblastic leukemia (T-ALL)." (PMID 33466790, 2021).
brain cancer (1 paper, 2025). A primary or metastatic malignant neoplasm affecting the brain. "Furthermore, USP24 inhibition induces ferroptosis in drug-resistant lung and brain cancer cells by elevating ACSL4 levels, activating autophagy, and facilitating GPX4 degradation." (PMID 40715045, 2025). "In addition, our findings are consistent with a previous study showing that pharmacological inhibition of USP24 promotes ferroptotic cell death in drug-resistant lung and brain cancer cells." (PMID 40715045, 2025).
colon cancer (1 paper, 2026). "USP32, USP1, USP37, USP12, and USP6 are elevated in macrophages, while USP32, USP9X, USP46, USP12, USP36, and USP24 are upregulated in classical monocytes of colon cancer relative to the control group." (PMID 41356798, 2026).
diabetic cardiomyopathy (1 paper, 2024). Diabetic cardiomyopathy is a disorder of the heart muscle in people with diabetes. "In line, a recent study shows that upregulation of the ubiquitin-specific protease 24 (USP24) in myocardial cells activates the NF-κB pathway in diabetic cardiomyopathy." (PMID 39372215, 2024).
fatty liver (1 paper, 2025). "Previous studies have shown that the upregulation of Mups inhibits hepatic steatosis, suggesting that targeting USP24 with USP24-i-101 may be beneficial for preventing hepatic steatosis." (PMID 40448065, 2025).
gastric carcinoma (1 paper, 2024). A carcinoma that arises from epithelial cells of the stomach. "USP24 promotes tumor growth in gastric carcinoma by stabilizing PLK1 to activate NOTCH1 and increase aerobic glycolysis." (PMID 39605891, 2024).
glioblastoma (1 paper, 2024). The most malignant astrocytic tumor (WHO grade IV). "To understand whether the USP24 inhibitor can kill TMZ‐resistant GBM cells, we evaluated the effect of NCI677397 on the survival of TMZ‐sensitive and TMZ‐resistant glioblastoma cells." (PMID 38140768, 2024).
glioma (1 paper, 2023). A benign or malignant brain and spinal cord tumor that arises from glial cells (astrocytes, oligodendrocytes, ependymal cells). "While linked to several DNA repair pathways, USP7 and USP24 expression was not significantly different among glioma groups or between glioma and the non-tumor control group in the Sun dataset, suggesting that these two DUBs may not be critical factors in DNA damage repair pathways in glioma." (PMID 37892185, 2023).
Immunodeficiency (1 paper, 2017). Failure of the immune system to protect the body adequately from infection, due to the absence or insufficiency of some component process or substance. "The injection of luciferase-expressing A549 cells with USP24 knockdown into severe combined immunodeficiency mice increased the tumor size and weight." (PMID 27991932, 2017).
Lewis lung carcinoma (1 paper, 2025). "To examine whether USP24-i-101 provoked antitumor efficacy in vivo, we performed a Lewis lung carcinoma (LLC)-allograft model." (PMID 40238877, 2025).
liver diseases (1 paper, 2025). "Clinical and animal tissue samples were examined with immunohistochemistry to identify the correlations between USP24 and metabolic-associated liver diseases." (PMID 40448065, 2025).
liver fibrosis (1 paper, 2024). "Therefore, it is worthy determining whether USP24 inhibitors can be a potential treatment for liver fibrosis as well as drug‐resistant cancers and we will persist in optimizing USP24 inhibitors in the future." (PMID 38140768, 2024).
lymph node metastasis (1 paper, 2025). "In addition, highly infiltrating USP24+PD-1+CD8+ T cells occurred in young patients and patients with adenocarcinoma and were associated with advanced tumor stage, larger primary tumor size, and lymph node metastasis." (PMID 40238877, 2025).
metabolic dysfunction-associated steatohepatitis (1 paper, 2025). Metabolic dysfunction-associated steatohepatitis (MASH, formerly known as nonalcoholic steatohepatitis or NASH) is a type of fatty liver disease. "USP24 was highly expressed in patients with metabolic dysfunction-associated steatohepatitis (MASH) and correlated with Cox2 and α-SMA levels." (PMID 40448065, 2025).